KRAS (KRas proto-oncogene, GTPase)
Diseases named in the same sentence as KRAS in open-access papers (continued):
Sharing a sentence is not in itself a finding about the gene and the disease.
pancreatic cancer (continued). "This proves the presence of amplifications in mutant KRAS already, during the early development of pancreatic cancer." (PMID 40227826, 2025). "AMPAR activation in pancreas tumor cells has also been reported to increase KRAS activity, a major driver of pancreatic cancer progression." (PMID 40143160, 2025). "This case demonstrates the potential of TCR T cell therapy to mediate significant tumor regression in KRAS-driven pancreatic cancer." (PMID 39744228, 2025). "The non-covalent KRAS G12D inhibitor MRTX1133 selectively blocks KRAS G12D activity with ultra-high affinity, inducing significant tumour regression in pancreatic cancer." (PMID 41463025, 2025). "We end with a discussion of lessons learned from the results from ongoing clinical trials, resistance mechanisms to KRAS inhibitors, and potential combination strategies to improve outcomes for patients with pancreatic cancer." (PMID 40829181, 2025). "In the presence of the Kirsten rat sarcoma viral oncogene homolog (KRAS) mutation, chronic inflammation is likely to lead to pancreatic cancer through increased reactive oxygen species (ROS) production which causes deoxyribonucleic acid damage." (PMID 39969214, 2025). "Significance: KRAS allelic status impacts pancreatic cancer progression and has the potential to guide effective treatment in a substantial subset of patients." (PMID 39412982, 2025). "KRAS allelic status impacts pancreatic cancer progression and has the potential to guide effective treatment in a substantial subset of patients." (PMID 39412982, 2025). "The development of inhibitors that selectively target the KRAS oncogene presents a viable path in the search for targeted treatments for pancreatic cancer." (PMID 40157967, 2025). "In clinical applications, nanoparticle albumin-conjugated paclitaxel (nab-paclitaxel, nab-PTX) has been successfully used for targeted therapy of KRAS-mutant cancers (e.g., pancreatic cancer and breast cancer)." (PMID 40723808, 2025). "Using a model of pancreatic ductal adenocarcinoma (PDAC), the major histological subtypes of pancreatic cancer, we found that oncogenic mutant KRAS reduces nuclear size." (PMID 40493403, 2025). "All 4 pancreatic cancer organoids pulsed with KRAS G12V 9-mer peptide greatly activated TCR-001–transduced allogeneic T cells, indicating sufficient levels of HLA-A*11:01 on these organoids." (PMID 39846249, 2025). "In contrast, treatment of KRAS-mutant Pa16C pancreatic cancer cells with the selective ERK1/2 inhibitor SCH772984 produced fewer than 40 DM CpGs." (PMID 39858030, 2025). "This dual-targeted therapeutic strategy holds promises for overcoming the challenges posed by KRAS-driven cancers, particularly in addressing the formidable obstacle of pancreatic cancer." (PMID 40382842, 2025). "In monoculture, most KRAS-mutant pancreatic cancer cell lines displayed strong KRAS dependency, consistent with previous reports." (PMID 41322195, 2025). "This study highlights the impact of Kras allelic imbalance and the critical role of WT KRAS in initiation, progression, and therapeutic response in pancreatic cancer." (PMID 39412982, 2025). "Continuously activated KRAS signaling in pancreatic cancer cells activates RREB1, which promote the binding of SMAD2/3 to the cis-regulatory regions of target genes." (PMID 39913299, 2025). "Studies with the KRas4B‐derived CaaX‐1 peptide (GLRKRLRKFRNK‐SKTKCVIM) revealed that this peptide altered downstream signaling of Ras proteins in KRas mutant pancreatic cancer cells." (PMID 40064612, 2025).
pancreatic cancer (continued). "Although the dependence of pancreatic cancer cells on KRAS has been debated, sustained KRAS activity is generally considered essential for tumor maintenance, making it a compelling therapeutic target." (PMID 41322195, 2025). "This proof-of-concept study evaluated the cytotoxic effects of ECT using bleomycin (BLM) or cisplatin (CDDP) in combination with sotorasib in KRAS G12C-mutated MIA PaCa-2 and KRAS G12D-mutated PANC-1 pancreatic cancer cell lines." (PMID 40806294, 2025). "We demonstrate the functional relevance of WT KRAS and present mechanisms that govern the role of WT KRAS in the processes of tumor initiation and progression in pancreatic cancer." (PMID 39412982, 2025). "In pancreatic cancer, where oncogenic KRAS is the main driver, tumor heterogeneity is a central hallmark and frequently associated with variable NF-kB signaling." (PMID 40294135, 2025). "Human EFR3A and EFR3B also regulate KRAS signalling at the plasma membrane in pancreatic cancer cells." (PMID 39991135, 2025). "Apart from an overall increase in KRAS mutations, we also noted a specific KRAS mutant allele, KRASG12R, which was significantly more prevalent in BAA patients with pancreatic cancer." (PMID 39699266, 2025). "We also analyze the importance of KRAS allelic imbalances in pancreatic cancer biology and their possible therapeutic implications." (PMID 40227826, 2025). "While T cells engineered to express this TCR specifically recognized all 5 tested human HLA-A*11:01+ and KRAS G12V+ pancreatic cancer organoids, the recognition was often modest, and tumor cell killing was observed in only 2 out of 5 organoids." (PMID 39846249, 2025). "Several additional cancer type-specific hallmarks emerged as significant, including genes related to KRAS in breast cancer, and Notch signaling in pancreatic cancer." (PMID 39939916, 2025). "Using this system, we demonstrated selective degradation of activated KRAS in multiple pancreatic cancer cell lines, along with suppression of downstream ERK signaling and proliferation." (PMID 41322195, 2025). "The current manuscript contributes with new knowledge applicable to current clinical efforts for treating pancreatic cancer, through a combination of targeted KRAS inhibition and chemotherapy." (PMID 40382842, 2025). "Therapeutic methods for pancreatic cancer patients with specific genetic mutations, such as BRCA1 or BRCA2 mutations and KRAS mutations, are currently being researched." (PMID 40948342, 2025). "DEG-KRAS induced degradation of active KRAS and suppressed proliferation in pancreatic cancer cell lines by reducing phospho-ERK levels." (PMID 41322195, 2025). "Natural inhibitors, such as manumycin, similarly inhibited KRAS-mutant pancreatic cancer cell lines." (PMID 40597785, 2025). "Exosome-mediated delivery of CRISPR-Cas9 plasmids targeting KRAS-G12D in pancreatic cancer cells achieved 58% gene knockdown." (PMID 40968311, 2025). "In our prospective pancreatic cancer biobank, from July 2019 to April 2020, there were 6 PDAC patients with KRAS G12V mutation and HLA-A*11:01 expression who had frozen PBMCs from approximately 10 mL of peripheral blood before or after surgery." (PMID 39846249, 2025). "Pancreatic cancer and other malignancies expressing KRAS G12D should be the subjects of prospective clinical studies to ascertain the therapy’s therapeutic potential." (PMID 40098955, 2025). "Approximately 92% of pancreatic cancer tissues carry various types of activating KRAS mutants, which appear at the early stage of the disease development." (PMID 41391757, 2025). "These new findings indicate that the down regulation of the RCC1/SIRT3 axis plays a significant role in KRAS-driven pancreatic cancer development." (PMID 41391757, 2025).
pancreatic cancer (continued). "The PDMR lines with KRAS G12D were among the most responsive to MRTX-1133 as a single agent with 377384-186-R-J1 pancreatic carcinoma mct-spheroids being most responsive." (PMID 40470182, 2025). "The KRAS status has a prognostic meaning; it has been shown that pancreatic carcinoma with wild‐type status for KRAS show a better course of the disease." (PMID 39807486, 2025). "Consistent with the established connections between KRAS and NRF2, it has been demonstrated that restricting glutamine can trigger pro-ferroptosis signals, such as GPX4 suppression, in pancreatic cancer cells with KRAS mutations." (PMID 39501138, 2024). "Pancreatic tumor development and onset entail the activation of oncogenic KRAS through metastasis, metabolic changes, treatment resistance, and modifications in signal transduction pathways." (PMID 38827026, 2024). "We showed that a retrospective, predictive simulation of the digital twins captured the cellular kinetics observed for KRAS G12D TCR-engineered T cell therapy in pancreatic cancer patients." (PMID 38278838, 2024). "Single-nucleotide mutations in the KRAS gene are detected in the majority of patients with pancreatic ductal adenocarcinoma (PDAC), the most common type of pancreatic cancer." (PMID 39478810, 2024). "Here, the authors report that ZDHHC20-mediated S-Palmitoylation of the m6A reader YTHDF3 stabilizes MYC mRNA to promote the progression of KRAS-mutant pancreatic cancer." (PMID 38821916, 2024). "Our data suggests KRAS mutations as a possible mechanism of primary and acquired resistance to anti-HER2 therapy in pancreatic cancer." (PMID 38406801, 2024). "KRAS (Kirsten rat sarcoma virus) pathway plays a pivotal role in the proliferation, invasion and metastasis of pancreatic cancer cells." (PMID 39200178, 2024). "For instance, sotorasib has shown improved response rates and extended progression-free survival in patients with KRAS(G12C)-mutant pancreatic cancer." (PMID 39001498, 2024). "Herein, we review approaches to KRAS targeting in pancreatic cancer to date and suggest some challenges for the future." (PMID 38576709, 2024). "In the current study, we investigated how HIPK2 contributes to oncogenic KRAS-driven tumorigenesis in the onset of pancreatic cancer." (PMID 39342278, 2024). "YAP1 is a context-specific driver for PDAC, and its activation allows pancreatic cancer cells to bypass oncogenic KRAS dependency." (PMID 39458993, 2024). "BRAF deletions are present in approximately 0.5%–1% of patients with pancreatic and thyroid cancers and account for about 5% in patients with KRAS wild-type pancreatic cancer." (PMID 39529955, 2024). "Within the spectrum of pancreatic neoplasms, pancreatic ductal adenocarcinoma (PDAC) constitutes over 90% of all cases, with Kirsten rat sarcoma viral oncogene homolog (KRAS) mutations detected in nearly 9 out of 10 PDAC instances." (PMID 39062169, 2024). "Our findings suggest that the interaction between FTH1 and PYCR1 leads to aberrant proline metabolism, subsequently inducing apoptosis in KRAS-mutant pancreatic cancer cells." (PMID 39294443, 2024). "The KRAS gene is a well-established key marker for developing various cancers, including colorectal, lung, and pancreatic cancers." (PMID 39409930, 2024). "Drugs such as sotorasib (FDA-approved) and adagrasib target KRAS as therapeutic interventions for various types of cancer, including pancreatic cancer." (PMID 39087024, 2024). "Critical molecular pathways driving pancreatic cancer development, including KRAS, Notch, and Hedgehog, are discussed." (PMID 39087024, 2024).
pancreatic cancer (continued). "This scenario was also observed in KRAS G12D–mutant pancreatic cancer cells, suggesting the general role of the Hippo-YAP/TAZ pathway in resistance to KRAS inhibitors." (PMID 39704172, 2024). "Our group has previously shown that the combination of KRAS G12C inhibitors with farnesyl-transferase inhibitors exerts synergistic anti-tumoral effects in several KRAS G12C tumor models, including pancreatic tumor cells." (PMID 39687047, 2024). "As the table shows, its mRNA level also positively correlates with PIK3CA significantly (p = 0.0002), a crucial downstream effactor of KRAS in pancreatic cancer." (PMID 39730634, 2024). "SIRT2 exerts significant influence on pancreatic cancer carcinogenesis by intricately regulating KRAS activity and its downstream oncogenic pathways." (PMID 39682281, 2024). "In this study, cationic bPEI-coated AuNPs were used for intracellular siRNA delivery targeting the KRAS gene in human pancreatic cancer cells (CAPAN-1)." (PMID 39553720, 2024). "As an adjuvant used in antitumor and anti-radiation therapies, CSI enhances erlotinib’s antitumor effects through inhibiting of the KRAS pathway, suggesting CSI’s potential as an adjunctive therapy specifically targeting KRAS-mutated pancreatic cancer." (PMID 39770538, 2024). "The mitogen-activated protein kinase pathway was a key oncogenic driver for KRAS WT pancreatic cancers." (PMID 39410042, 2024). "The TCRs were derived from healthy donors or patients with pancreatic cancer who had received a vaccine against mutant KRAS." (PMID 39484723, 2024). "Approximately 95% of pancreatic tumours exhibit RAS mutations, with KRAS alterations being the most prevalent, accounting for 85% of cases." (PMID 38384463, 2024). "Again, on-target efficacy was suggested by the apparent lack of any therapeutic efficacy of BI-3406, Binimetinib, or radiation therapy as well as combination regimens in KRAS wild type BxPC3 pancreatic cancer cells." (PMID 38892436, 2024). "The dual targeting of KRAS mutations and EGFR demonstrated greater therapeutic effectiveness in pancreatic cancer management compared to single-agent approaches." (PMID 39770538, 2024). "More recent evidence strongly suggests therapeutic synergism of KRAS inhibition in combination with immune checkpoint blockades in pancreatic cancer." (PMID 38892436, 2024). "Nuclear factor erythroid 2(NRF2) can activate metabolic reconnection and increase the pathway involved in glutamine metabolism, which inhibits the chemotherapy resistance of KRAS mutant pancreatic cancer." (PMID 39588377, 2024). "Pancreatic cancer cells are addicted to glutamine and cystine metabolism, which is regulated by the KRAS/NRF2 axis." (PMID 38908072, 2024). "Mouse models were employed to investigate the cooperative impact of p16 inactivation and KRAS activation on pancreatic tumor development." (PMID 38666907, 2024). "In the present study, we discover that ZDHHC20, a protein upregulated by KRAS, is abnormally overexpressed and predict an unfavorable prognosis in pancreatic cancer." (PMID 38821916, 2024). "We decided to use CR-1-31-B, a synthetic rocaglate with more favorable pharmacokinetic properties than RocA, which has already demonstrated antitumor activity in mouse models, e.g., in KRAS-driven pancreatic cancer." (PMID 39436655, 2024). "In the pursuit of targeted therapies for KRAS-mutant pancreatic cancer, diverse strategies have emerged, each being promising in addressing the challenges posed by this notoriously resistant oncogene." (PMID 38666907, 2024). "We show its utility by generating a SOCS7-based KRAS degrader that inhibits mutant KRAS pancreatic cancer cells’ proliferation." (PMID 38746666, 2024).
pancreatic cancer (continued). "KRAS wild-type (wtKRAS) pancreatic cancer patients have been consistently shown to have improved overall survival and disease-free survival." (PMID 38610868, 2024). "Further, we design a biologically active YTHDF3-derived peptide to competitively inhibit YTHDF3 palmitoylation mediated by ZDHHC20, which in turn downregulates MYC expression and inhibits the progression of KRAS mutant pancreatic cancer." (PMID 38821916, 2024). "Within the scope of eight genes associated with pancreatic cancer, we detected two variants, namely rs6465133 (SRI) (p = 0.001) and rs61759623 (KRAS) (p = 0.005), which exhibit the potential to differentiate between PCAND and T2DM." (PMID 39526476, 2024). "Here, we provide evidence for the feasibility of this combinational approach to break down resistance in KRAS G12D mutant pancreatic cancer." (PMID 39687047, 2024). "A noteworthy advancement in targeted therapy is MRTX1133, demonstrating potential in inhibiting KRAS G12D and introducing novel avenues for pancreatic cancer treatment." (PMID 38250721, 2024). "Autophagy pathways have been described to be upregulated in cell culture and xenograft models of pancreatic cancer in response to inhibition of MEK-ERK signaling downstream of mutant KRAS." (PMID 39352477, 2024). "Murine models have convincingly demonstrated that oncogenic KRAS is crucial for both the formation of these precursors and the initiation and maintenance of invasive pancreatic cancers." (PMID 39457488, 2024). "We also found synergistic effects using additional FTis and KRAS-G12C inhibitors as well as in KRAS-G12C mutant colorectal and pancreatic cancer models." (PMID 38278976, 2024). "High lipid levels can enhance expression of oncogenic KRAS, resulting in more fibrotic stroma that enhances the tumor progression and stimulates the proliferation of tumor cell lines in pancreatic cancer." (PMID 37505298, 2024). "Unlike in NSCLC, G12C mutations represent only a minor fraction of KRAS mutations detected in PDAC, yet this therapeutic approach has been evaluated in gastrointestinal carcinomas including pancreatic cancer, albeit with limited success." (PMID 38892436, 2024). "Mutations in the KRAS gene are found in over 90% of pancreatic ductal adenocarcinomas [PDAC], the most common type of pancreatic cancer." (PMID 39409171, 2024). "In this study, we investigated the metabolomic profiles of pancreatic cancer cells based on their KRAS genetic status." (PMID 38672219, 2024). "In particular, KRAS plays a significant role in pancreatic cancer due to the dysregulation of key cellular processes including glycolysis, autophagy and macropinocytosis by altering cellular metabolism and supporting the tumor microenvironment." (PMID 38791940, 2024). "Although NRG1 gene rearrangement is uncommon in pancreatic cancer, it tends to be enriched in younger patients with KRAS wild-type pancreatic cancer." (PMID 38627681, 2024). "The metabolomic profiles of both pancreatic cancer cell lines were distinctly characterized by their KRAS genetic status." (PMID 38672219, 2024). "KRAS mutant is a known oncogene driving pancreatic cancer, and inhibition of KRAS mutant expression at the mRNA level is an effective anti-tumor strategy." (PMID 38524179, 2024). "More importantly, CRISPR-Cas13a-mediated mRNA downregulation can induce apoptosis of mouse tumor cells and cause significant tumor atrophy in vitro, and CRISPR-Cas13a knockdown of KRAS-G12D can block the proliferation of pancreatic cancer cells." (PMID 38524179, 2024). "From cluster 1, it can be inferred that the focus likely pertained to gene expression and biological properties of KRAS in various cancer cells encompassing breast cancer, cholangiocarcinoma, and pancreatic cancer." (PMID 38706597, 2024).